MLDHR (mitochondrial lactate dehydrogenase regulator)
Description:
Inhibits lactate dehydrogenase (LDH)-mediated conversion of lactate to pyruvate in mitochondria by competing with mitochondrial LDH for binding to NAD(+). Also inhibits cellular lactate utilization.
Synonyms: MP31; PTENURF
Tractability: No criterion of Open Targets' tractability assessment is met for any kind of drug.
Gene: Protein-coding gene on chromosome 10 (87,863,559 to 87,863,654, forward strand). Ensembl gene ENSG00000289051.
Subcellular location: Mitochondrion
Gene Ontology:
Molecular function: L-lactate dehydrogenase inhibitor activity; protein binding
Biological process: negative regulation of oxidative phosphorylation
Cellular component: mitochondrion
Diseases named in the same sentence as MLDHR in open-access papers:
MLDHR is named in the same sentence as 2 diseases in open-access papers, as found by Europe PMC text mining. Sharing a sentence is not in itself a finding about the gene and the disease.
MLDHR shares sentences with these, for which no sentence is quoted: glioblastoma (5 papers); cancer (2).